TPH1 (tryptophan hydroxylase 1)
Diseases named in the same sentence as TPH1 in open-access papers (continued):
Sharing a sentence is not in itself a finding about the gene and the disease.
Stroke (5 papers, 2017 to 2022). Sudden impairment of blood flow to a part of the brain due to occlusion or rupture of an artery to the brain. "No statistical correlation was found between combined genotypes of the c.*456G > A (rs10988134) – KAT1 and c.-173A > T – TPH1 (rs10488682) polymorphisms and the development of stroke." (PMID 31817010, 2019). "There was a link between an increased risk of stroke and the frequency of the C/C-C/C, A/A-C/C genotypes of c.804-7C > A – TPH1 (rs1799913) and c.-1449C > A – TPH2 (rs7963803), while the C/A-C/C and A/A-C/A genotypes reduced this risk." (PMID 31817010, 2019). "The C/C-T/T and C/A-T/T genotypes of c.-1849C>A – IDO1 (rs3824259) and c.-1668T > A – TPH1 (rs623580) were associated with a reduced risk of stroke, whereas the C/A-T/A and C/A-A/A genotypes caused an increase of the risk in the Polish population." (PMID 31817010, 2019). "The T/T-T/T, C/C-A/T, C/C-T/T combined genotypes of c.975-7T > C– KAT2 (rs1480544) and c.-173A > T – TPH1 (rs10488682) were linked with an increased risk of stroke occurrence, while the T/C-T/T genotype of the same polymorphism combination decreased this risk." (PMID 31817010, 2019). "We found that the G/C-T/T, C/C-T/T and C/C-T/A genotypes of c.-1493G > C – IDO1 (rs10089084) and c.-1668T>A – TPH1 (rs623580) reduced the risk of stroke, whereas the G/G-T/A genotype increased this risk." (PMID 31817010, 2019). "Among the studied SNPs, the heterozygote and the C allele of c.804-7C > A – TPH1 (rs1799913) were associated with a reduced risk of stroke occurrence, and the homozygote A/A and the A allele of the same SNP decreased this risk." (PMID 31817010, 2019). "The T/T-A/A, C/C-C/C and C/C-A/A genotypes of c.975-7T > C– KAT2 (rs1480544) and c.804-7C > A - TPH1 (rs1799913) caused an increase of the risk of stroke." (PMID 31817010, 2019). "In the case of the c.-1849C > A – IDO1 (rs3824259) and c.804-7C > A – TPH1 (rs1799913) polymorphisms, the C/C-C/A and C/A-C/A combined polymorphisms were linked with a reduction of stroke risk about 20 times (p = 0.004) and 10 times (p < 0.001), respectively." (PMID 31817010, 2019). "The results demonstrated that the T/T genotype and T allele of c.-1668T > A – TPH1 (rs623580) were negatively correlated with stroke, whereas the A/A, T/A and A allele of the same polymorphism were positively correlated with the disease." (PMID 31817010, 2019). "Moreover, we found that the T/T-T/A, C/C-T/A, C/C-A/A genotypes of c.975-7T > C– KAT2 (rs1480544) and c.-1668T > A – TPH1 (rs623580) increased the risk of stroke about threefold (p = 0.016), fourfold (p < 0.001) and 27-fold (p < 0.001), respectively." (PMID 31817010, 2019). "We also confirmed that the G/G-C/A and G/A-C/A combined genotypes of c.*456G > A (rs10988134) – KAT1 and c.803+221C > A – TPH1 (rs1800532) were related with a decreased risk of stroke, but the G/G-A/A and G/A-C/C combined genotypes of the same polymorphism increased this risk." (PMID 31817010, 2019). "Similarly, in the case of the TPH1 polymorphism, we confirmed that the A/A genotype increased the risk of stroke." (PMID 31817010, 2019). "Additionally, we found that the only C/A-T/T genotype of the c.-1849C > A – IDO1 (rs3824259) and c.-173A>T – TPH1 (rs10488682) combined polymorphisms elevated the risk of stroke development." (PMID 31817010, 2019). "The G/G-A/T and G/G-T/T genotypes of c.-1493G>C – IDO1 (rs10089084) and c.-173A > T – TPH1 (rs10488682) caused an increase of the risk of stroke, whereas the C/C-A/T and C/C-T/T genotypes of the same combined polymorphisms brought about a reduction of this risk." (PMID 31817010, 2019). "Additionally, the presence of the G/G-T/T and G/A-T/T combined genotypes of the c.*456G > A (rs10988134) – KAT1 and c.-1668T > A – TPH1 (rs623580) polymorphisms reduced the risk of stroke development, while the G/G-T/A genotype increased this risk in the studied population." (PMID 31817010, 2019).
Stroke (continued). "Moreover, the T/C-C/A combined genotypes c.975-7T > C– KAT2 (rs1480544) and c.803+221C > A – TPH1 (rs1800532) caused a more than 20-fold reduction of the stroke risk in the Polish population (p = 0.001), whereas the C/C-C/C genotype increased this risk about ten times (p = 0.001)." (PMID 31817010, 2019). "In rats, the mRNA level of TPH1 decreases in the brain after stroke but acupuncture intervention significantly increases TPH1 levels." (PMID 36037970, 2022). "Expression changes of TPH1 in relation with stroke have been investigated in animal models of the disease." (PMID 34680558, 2021). "We found that the C/C-G/G combined genotype of the c.804-7C>A – TPH1 (rs1799913) and c.-844G > T – TPH2 (rs4570625) polymorphisms were associated with an increased risk of stroke." (PMID 31817010, 2019). "In the case of c.803 + 221C > A – TPH1 (rs1800532) and c.-844G > T – TPH2 (rs4570625), the C/C-G/G and C/A-G/G were linked with the risk of stroke elevated by more than 10 times (p < 0.001)." (PMID 31817010, 2019). "Moreover, we observed that the C/C-C/C combined genotype of the c.803 + 221C > A – TPH1 (rs1800532) and c.-1449C > A – TPH2 (rs7963803) polymorphisms were associated with an increased risk of stroke, whereas the C/A-C/A genotypes reduced the risk." (PMID 31817010, 2019). "So far, we have been the first to investigate that c.-173A > T SNP of TPH1 may contribute to the development of stroke." (PMID 31817010, 2019). "Moreover, we found that the T/T-C/C genotype of c.-173A > T – TPH1 (rs10488682) and c.-1449C > A – TPH2 (rs7963803) was linked with an elevated risk of stroke development, whereas the A/T-C/A genotype caused a decrease of this risk by nearly fifteen times." (PMID 31817010, 2019). "Notably, in our and other previous studies, the level of TPH1 in brain tissue was found to be significantly decreased in rats after stroke, suggesting that TPH1 may have a protective effect on nerve damage following stroke." (PMID 36037970, 2022). "As far as we are aware, studies focusing on changes of TPH1 expression in stroke patients have not been conducted so far." (PMID 34680558, 2021). "Furthermore, we examined the mRNA levels of TPH1, IDO1 and KYAT1 genes in peripheral venous blood with the aim of assessing (i) whether there are changes in their expression during the course of stroke and (ii) does any of their investigated SNPs have an impact on gene expression." (PMID 34680558, 2021). "Tryptophan hydroxylase 1 (TPH1) is involved in a variety of mental and neurobehavioral processes, but its effects on stroke have not yet been reported." (PMID 36037970, 2022).
type 2 diabetes (5 papers, 2015 to 2022). "Additionally, we identified HDAC1/PKA signaling as a novel regulatory axis for Tph1 expression, thus providing a potential therapy for type 2 diabetes characterized by impaired β-cell functional compensation." (PMID 32641996, 2020).
alcohol (4 papers, 2018 to 2026). "However, in our study, we found that AKK did not affect the level of TPH1 in the gut of the NIAAA mice and the chronic alcohol-treated mice; in the CUMS mouse model, AKK intervention had decreased the expression of TPH1 in the gut." (PMID 37668965, 2024).
cholangiocarcinoma (4 papers, 2021 to 2025). A carcinoma that arises from the intrahepatic biliary tree (intrahepatic cholangiocarcinoma) or from the junction, or adjacent to the junction, of the right and left hepatic ducts (hilar cholangiocarcinoma). "Real-time PCR analysis showed an increased expression of TPH1 and decreased Monoamine Oxidase A (MAO-A) expression in human cholangiocarcinoma cell lines compared with nonmalignant cell lines." (PMID 33525332, 2021).
Crohn disease (4 papers, 2013 to 2025). A gastrointestinal disorder characterized by chronic inflammation involving all layers of the intestinal wall, noncaseating granulomas affecting the intestinal wall and regional lymph nodes, and transmural fibrosis. "In patients with Crohn’s disease, TPH1 expression in the colon was significantly elevated in inflamed regions compared to noninflamed regions and healthy controls." (PMID 41465348, 2025). "The expression of TpH1 and the level of 5-HT increase in Crohn's disease but UC has shown opposite results." (PMID 34721011, 2021). "Thus, Crohn’s disease patients who experience IBS-like symptoms are characterized by increased expression of tryptophan hydroxylase 1 in the colon." (PMID 23691109, 2013).
mood disorder (4 papers, 2013 to 2025). A cognitive disorder a disturbance in which the person's mood is hypothesized to be the main underlying feature. "Especially, TPH-2 is expressed in peripheral tissues of the brain, which is important in the regulation of mood disorders, whereas TPH-1 is not significantly expressed in the brain." (PMID 30854015, 2019).
pancreatic cancer (4 papers, 2021 to 2025). "In Tph1‐knockout mice, peripheral 5‐HT levels are significantly decreased, and in Tph1‐knockout mice with colorectal or pancreatic cancer, tumor growth is markedly slower." (PMID 40937192, 2025). "Also, we investigated whether long-term exposure to TPH1-derived or exogenous 5-HT induces pancreatic cancer cells to a gemcitabine-resistant phenotype, and the mode of operation of the TPH1-5-HT-5-HT7 axis." (PMID 34771469, 2021). "In pancreatic cancer tissues, levels of 3-IAA, 5-HT, KYNU, IDO, and TPH1 are significantly elevated, while levels of MAOA, 3-hydroxyanthranilic acid 3,4-dioxygenase (HAAO), and quinolinic acid phosphoribosyltransferase (QPRT) are markedly downregulated." (PMID 38462620, 2024). "TPH1 expression is positively correlated with TNM stage and tumor size, and IDO expression is elevated in pancreatic cancer metastases." (PMID 38462620, 2024). "In pancreatic cancer, long-term exposure to 5-HT in an autocrine or paracrine manner induced PRC2-independent EZH2 action that supported the TPH1-5-HT7 axis, leading to gemcitabine resistance and a CSC population increase." (PMID 34771469, 2021). "High levels of IDO, TPH1, HTR2B, AhR, and Kyn predict a poor prognosis in pancreatic cancer, whereas MAOA expression is negatively correlated with TNM stage and tumor size in pancreatic cancer, predicting a favorable prognosis." (PMID 38462620, 2024). "Given the report, a future study is also required to determine whether EZH1 also contributed to the modulation of TPH1 and 5-HT7 pathways in pancreatic cancer cells." (PMID 34771469, 2021). "Furthermore, the inhibitor of EZH2, TPH1, or 5-HT7 effectively regressed pancreatic tumor growth in a xenografted mouse tumor model." (PMID 34771469, 2021).
renal fibrosis (4 papers, 2022 to 2024). A final common manifestation of a wide variety of chronic kidney diseases characterized by glomerulosclerosis and tubulointerstitial fibrosis. "Poricoic acid A (PAA), derived from Poria cocos, has been identified as a modulator of TPH-1 expression, demonstrating its efficacy in attenuating renal fibrosis, as well as enhancing melatonin’s inhibitory effects on the transition from AKI to CKD." (PMID 39619610, 2024). "In addition, our recent studies showed that poricoic acid A, as a modulator of tryptophan hydroxylase-1 expression, inhibited renal fibrosis by regulating β-catenin protein stability and induced transcription." (PMID 36059935, 2022). "In the UUO mice model, poricoic acid A reduced the activity of the Wnt/β-catenin signaling pathway by enhancing the expression of tryptophan hydroxylase-1 (TPH-1), and also inhibited renal cell injury and fibroblast activation, exerting an anti-renal fibrosis effect." (PMID 35978370, 2022).
autoimmune disease (3 papers, 2014 to 2025). A disorder resulting from loss of function or tissue destruction of an organ or multiple organs, arising from humoral or cellular immune responses of the individual to their own tissue constituents. "In this study, authors found that Tph1 was able to regulate T cell polarization and ameliorate autoimmune disease in mice." (PMID 32823705, 2020). "Again, Tph1−/− mice were protected from an inflammatory disorder, in this case the autoimmune disease asthma." (PMID 24520366, 2014). "A novel hypothesis may relate vitamin B6 and Trp catabolism to inflammatory status, knowing that two major Trp catabolic enzymes, IDO or Tph1, are especially known to regulate peripheral tolerance in infections or autoimmune diseases." (PMID 32823705, 2020). "Interestingly, Tph1 activation by NAD+ was found to protect against multiple sclerosis, an autoimmune disease where autoreactive T cells progressively react against self-antigens." (PMID 32823705, 2020).
behavioral disorders (3 papers, 2005 to 2024). "The rs4290270 polymorphism has been reported to interact with genetic variants also in other genes in influencing behavioral disorders—specifically, with polymorphism in the TPH1 gene (encoding a peripheral isoform of TPH) in influencing heroin addiction." (PMID 36833340, 2023).
colon cancer (3 papers, 2019 to 2022). "Our results confirmed that SLC7A5, SLC1A5, TDO2, IDO1, and AHR were all elevated in colon cancer, while TPH1 was reduced." (PMID 31416966, 2019). "We performed IHC for TDO2, TPH1, AHR, serotonin, and TPH2 in paraffin-embedded patient-derived normal and colon cancer tissues to confirm our TCGA results." (PMID 31416966, 2019). "To validate these results, we performed RT-qPCR for SLC1A5, SLC7A5, TPH1, TDO2, IDO1, AHR, and MYC in colon cancer and normal tissue of the same patients." (PMID 31416966, 2019). "Additionally immunohistochemical detection of colon cancer micro array revealed that the expression of serotonin metabolism-related enzymes (TPH1, SERT, MAOA, and MAOB) were overexpressed in human colon cancer tissues than in the adjacent normal tissues." (PMID 34006301, 2021).
glioma (3 papers, 2022 to 2025). A benign or malignant brain and spinal cord tumor that arises from glial cells (astrocytes, oligodendrocytes, ependymal cells). "Herein, we extended the prior work, and our findings underlined TPH-1 participation in regulating the proliferative properties, migratory capacity, and chemotherapeutic sensitivity of glioma cells." (PMID 35473609, 2022). "To further investigate the clinical implications of the serotonergic pathway, we performed analysis using TCGA dataset, which suggested that a high TPH-1 expression was associated with a poor prognosis in glioma patients." (PMID 35473609, 2022). "We aimed to elucidate the mechanism underlying TPH-1-induced glioma progression." (PMID 35473609, 2022). "Therefore, it was imperative to disentangle the mechanisms underlying TPH-1-mediated regulation of glioma development." (PMID 35473609, 2022). "Intriguingly, many high-grade gliomas do overexpress TPH1, boosting serotonin production that can in turn augment NF-κB signaling and tumor invasion." (PMID 40705199, 2025). "In the present study, we shed light on tumor metabolism and aimed to investigate the role of tryptophan hydroxylase 1 (TPH-1) in the advancement of glioma." (PMID 35473609, 2022). "Taken together, these results implied that TPH-1 played a role in promoting glioma progression and was correlated with poor progression." (PMID 35473609, 2022). "Intriguingly, an elevated expression of TPH-1 was observed in glioma tissues relative to the normal tissues, suggesting the potential role of TPH-1 in promoting glioma development." (PMID 35473609, 2022). "We also examined the tumor growth and survival time in a mouse model of glioma treated with chemotherapeutic agents and a TPH-1 inhibitor." (PMID 35473609, 2022). "Our previous results suggested the role of TPH-1 and serotonin in promoting glioma cell proliferation." (PMID 35473609, 2022). "Using The Cancer Genome Atlas (TCGA) database, we observed that TPH-1 expression was markedly augmented in glioma tissues and that patients with a high TPH-1 expression exhibited poorer overall survival rates." (PMID 35473609, 2022). "Our study further indicated that TPH-1 drove glioma development in an L1-cell adhesion molecule (L1-CAM)/NF-κB dependent manner." (PMID 35473609, 2022). "The results of both clinical and experimental data showed that excess TPH-1 expression resulted in sustained glioma progression and a dismal overall survival in these patients." (PMID 35473609, 2022). "We showed that TPH-1 played a stimulatory function for glioma cell proliferation, motility, and drug resistance." (PMID 35473609, 2022). "Herein, the levels of TPH-1 expression in glioma tissues were evaluated using The Cancer Genome Atlas (TCGA) database." (PMID 35473609, 2022). "Our study focused on the role of TPH-1 in glioma and the findings indicated that TPH-1 hydroxylated Trp led to serotonin production, thereby driving robust tumor growth and progression." (PMID 35473609, 2022). "In an attempt to further confirm the correlation between TPH-1 expression and serotonin production in vivo, we collected 20 tumor tissues from glioma patients and determined the expression of TPH-1 and serotonin production by immunofluorescence and ELISA." (PMID 35473609, 2022). "Taken together, these data suggested that TPH-1 facilitated cellular proliferation, migration, and chemoresistance in glioma through the serotonin/L1CAM/NF-κB pathway." (PMID 35473609, 2022). "In light of the limitations to previous studies, herein, we highlight the relevance of TPH-1 in glioma advancement." (PMID 35473609, 2022). "Given the poor prognosis of glioma patients with a high TPH-1 expression, we reasonably speculated whether TPH-1 expression could influence the cellular proliferation/migration in glioma." (PMID 35473609, 2022). "This led us to reasonably speculate that TPH-1 may mediate the Trp hydroxylation to produce serotonin, thereby promoting glioma development." (PMID 35473609, 2022).